RAB27B (RAB27B, member RAS oncogene family)
Diseases named in the same sentence as RAB27B in open-access papers (continued):
Sharing a sentence is not in itself a finding about the gene and the disease.
cancer (continued). "The majority of clinicopathological findings indicate that Rab27A and Rab27B have oncogenic roles in cancer." (PMID 30081925, 2018). "Rab proteins of the endocytosis and exocytosis pathways both play critical roles in cancer progression, and Rab27B has a significant relationship with several types of human cancer." (PMID 25382899, 2014). "Rab proteins of the endocytosis and exocytosis pathways both play critical roles in cancer progression, and a few studies have investigated the role of Rab27B in several types of human cancer." (PMID 25382899, 2014). "Recently, it is reported that aberrant expression of Rab27b contributes to cancer progression and increased Rab27b expression correlates with lymph node metastasis." (PMID 25580113, 2014). "Although some studies have reported that positive staining of Rab27B is mainly localized in the cytoplasm of cancer cells, we observed dominant nuclear staining of Rab27B in the present study." (PMID 25382899, 2014). "Future research aims to unravel the substantial contribution of different Rab27B-steered secretory pathways to the development of an extracellular signaling network for cancer progression." (PMID 23665896, 2013). "An interesting phenomenon was that Rab27B expression appeared to increase incrementally with the magnitude of cancer progression in tissue ( P < 0.05." (PMID 23217148, 2012). "Because of the relationship between Rab27B and cancer progression, elucidating the role of exosomes in metastatic niche formation will be the next step forward in cancer research." (PMID 26082068, 2012). "We observed that the increased expression of Rab27B was dependent upon the magnitude of cancer progression (P < 0.001)." (PMID 23217148, 2012). "We seek to know how metformin induces exosome biogenesis and secretion in cancer cells; and found that the mRNA level of genes related to exosome biogenesis and secretion such as Alix, Rab27b, CD81, CD63, and Lamp-2 concomitantly with CD63 protein level up-regulated in cells treated with metformin." (PMID 38627767, 2024). "The findings suggest that targeting RAB27B could provide a promising therapeutic strategy for NRAS-driven cancers." (PMID 37317974, 2023). "The findings suggest that targeting RAB27B by blocking the palmitoylation of NRAS could provide a promising therapeutic strategy for NRAS-driven cancers." (PMID 37317974, 2023). "NSCLC progression has been attributed to stem-like properties of cancer cells; therefore, we sought to establish whether RAB27B plays a major role in the promotion of these properties." (PMID 37077938, 2023). "In addition, cancer cells can secrete a large number of exosomes, because the overexpressed Rab27a and Rab27b proteins in cancer cells are involved in the process of exosome release." (PMID 35701788, 2022). "RAB27B has been reported to regulate apoptosis in some cancers." (PMID 35164665, 2022). "The difference between the results of the previous study and our results suggests that the role of Rab27b in the radiation response may differ, depending on the type of cancer." (PMID 33409495, 2020). "However, more studies are needed to confirm the roles of Rab27A/B in cancer because Rab27A and Rab27B have been reported to have cancer type-dependent functions; the roles of Rab27A/B in cancer remain elusive." (PMID 30081925, 2018). "For another, Rab27b may have multiplicate properties in different cancer types or under different circumstances." (PMID 30627227, 2018). "Rab27A and Rab27B promote exosome secretion in various types of cancer." (PMID 30081925, 2018). "Increased HSP90α-induced MMP-2 activation may mediate the effects of Rab27B on promoting cancer metastasis." (PMID 30081925, 2018). "Although it is reported that Rab27b expression was located in the cytoplasm of cancer cells in some previous studies, the latest research stated that Rab27b was also expressed in stromal cancer cells with high staining and this result was consistent with our present findings." (PMID 25580113, 2014).
cancer (continued). "It has been reported that increased Rab27B expression correlates with the degree of cancer progression and might facilitate the invasive phenotypes." (PMID 25382899, 2014). "Furthermore, Rab27B has also been identified as a predictor of prognosis in certain human cancers, and high expression leads to unfavorable survival." (PMID 25382899, 2014). "Importantly, they showed that administration of a sEV release inhibitor or implantation of cancer cells that release a limited amount of sEVs (mEERL Rab27a+/- and Rab27b-/- cells) attenuated the development of pain, thus providing convincing evidence for a significant role of cancer sEVs in pain." (PMID 39811726, 2024). "Specifically, whether the increased level of RAB27B found packaged in CSC-derived EVs influences the loading of specific biomolecules that may contribute to the conversion of BCCs to more stem-like cancer cells warrants further study." (PMID 37077938, 2023). "According to previous studies, Rab27a and Rab27b have structural similarities and are functionally similar in that they are involved in the transport and exocytosis of secretory vesicles in various cell types, including melanocytes, neutrophil, and cancer cells." (PMID 32784729, 2020). "Here, we report that expression of RAB27B, a small GTPase, is significantly upregulated in NSCLC CSCs when compared with bulk cancer cells (BCC)." (PMID 37077938, 2023). "Taken together, our results indicate that RAB27B is required for maintenance of a highly tumorigenic, cancer-initiating, invasive stem-like cell population in NSCLC and RAB27B is involved in propagating EV-mediated communication from NSCLC CSCs to BCCs." (PMID 37077938, 2023). "Our results demonstrate that RAB27B is upregulated in NSCLC CSCs and mediates an increase in EV release that propagates EV-mediated communication between CSCs and bulk cancer cells (BCC) that confers a stem-like phenotype in NSCLC cells." (PMID 37077938, 2023). "As such this has been shown in some cancers for e.g. ESCRT components, syntenin, heparanase, small GTPases (such as Rab27A and Rab27B), SNARE proteins (such as SNAP23)." (PMID 35898875, 2022). "In the cancer cachexia model, inhibiting LLC-EVs release by knocking down the expression of Rab27A and Rab27B can alleviate muscle wasting." (PMID 33510128, 2021). "For example, our data demonstrate that miR-21 and miR-155 are related with progression and invasion of GBM by regulating marker genes of cancer metastasis, such as LHX6, DRD1, NEUROG1 and RAB27B, and thereby contributing to GBM patient survival." (PMID 29312626, 2017). "Altered expression of RAB27A/B is observed in various human cancers and has been linked to cancer progression in NSCLC, although the mechanism by which RAB27B affects NSCLC is not known." (PMID 37077938, 2023). "By inhibiting these pathways, Rab27B and SRR could be effective and functional downstream targets of miR-193a-3p and miR-193a-5p in the mechanism of cancer metastasis." (PMID 26913720, 2016). "Both short isoforms of WDPCP and RAB27B, which are induced by PRMT4, 5, and 7, promoted the proliferation of MCF7 cells, whereas the long isoform did so to a much lesser extent or even exhibited an opposite effect, thus linking aberrant splicing to cancer cell growth." (PMID 33782401, 2021).
infection (4 papers, 2022 to 2025). The state of being infected such as from the introduction of a foreign agent such as serum, vaccine, antigenic substance or organism. "Rab27bfl/fl and Rab27b-deficient cells had similarly high infection rates at the time of transplantation, as evidenced by the percentage of GFP+ cells." (PMID 37317963, 2023). "Other genes, such as EVA1A, which is involved in the regulation of autophagy and apoptosis, and ECE1 and Rab27b, which are associated with the growth, invasion, and metastasis of a variety of tumors, were also overexpressed in the context of vPdR-H30K-5U infection." (PMID 40006915, 2025). "RAB27B also plays a role in the exocytosis of neutrophil granules, suggesting that cleavage of RAB27B could also disrupt the immune response to infection." (PMID 35379171, 2022). "We probed UPEC-infected BECs with antibodies against RAB27b and LC3A/B+ compartments, at different time-points following infection." (PMID 37167325, 2023).
gastrointestinal tumor (1 paper, 2014). "However, the association between Rab27B expression and clinical features to determine its clinicopathological significance in gastrointestinal tumor (GIST) has not been investigated." (PMID 25382899, 2014).
RAB27B also shares sentences with these, for which no sentence is quoted: cervical cancer (4 papers); Parkinson disease (3); nervous system diseases (2); acute lymphoblastic leukemia (1); asthma (1); astrocytoma (1); autism (1); chronic myeloid leukemia (1); dementia (1); esophageal cancer (1); frontotemporal dementia (1); gastrointestinal stromal tumor (1); Huntington disease (1); hyperlipidemia (1); major depressive disorder (1); non-small cell lung carcinoma (1); osteoarthritis (1); pituitary adenoma (1); psoriasis (1); rectal adenocarcinoma (1); rectal cancer (1); squamous cell carcinoma (1).